CTLA4 (cytotoxic T-lymphocyte associated protein 4)
Diseases named in the same sentence as CTLA4 in open-access papers (continued):
Sharing a sentence is not in itself a finding about the gene and the disease.
cancer (continued). "The use of ICIs—monoclonal antibodies targeting programmed death protein 1 (PD-1), programmed death protein 1 ligand (PD-L1) and CTLA-4—has yielded impressive results in many settings and is currently a cornerstone in cancer treatment, including BC." (PMID 36131924, 2022). "Specific immune checkpoint inhibitors targeting PD-1 and CTLA-4 pathways crucially ameliorated the prognosis of patients with multiple types of cancer." (PMID 36335094, 2022). "Extensive interest in cancer immunotherapy is reported according to the clinical importance of CTLA-4 and PD-1/PD-L1 in immune checkpoint therapies." (PMID 35603151, 2022). "CPIs targeting PD-1 and CTLA-4, the current standards of cancer immunotherapy, have the limitation of a low response rate." (PMID 35136110, 2022). "These drugs are monoclonal antibodies targeting im-mune-inhibiting proteins on cancer cells, such as CTLA-4 and PD-1/PD-L1." (PMID 36358869, 2022). "According to clinical research, anti-PD-1/PD-L1 and anti-CTLA-4 mAbs greatly enhance the therapeutic effects of cancer vaccines in PCa." (PMID 36016257, 2022). "Antibodies that target PD-1/PD-L1 and CTLA-4 have already shown significant efficacy in treating patients with a variety of cancers." (PMID 35054524, 2022). "Allison and Honjo’s discovery of T-cell immune checkpoints CTLA-4 and PD-1, which awarded them the Nobel Prize in Physiology or Medicine in 2018, propelled the cancer immunology field into the present era of cancer immunotherapy." (PMID 36135216, 2022). "Checkpoint inhibitors such as nivolumab (anti-PD-1), and ipilimumab (anti-CTLA-4) that prevent PD-1/PD-L1, PD-1/PD-L2, and CTLA4/B7 interactions are now FDA approved for treating a wide range of cancers." (PMID 36480493, 2022). "The central role of the co-inhibitory receptors also referred to as inhibitory immune checkpoints, including PD-1 and CTLA-4 has become especially evident with the cancer treatments targeting these receptors." (PMID 35784333, 2022). "Cancer cell mediated upregulation of CTLA-4 on T-cells augments the recruitment of immunosuppressive T-cells." (PMID 35448174, 2022). "Cancer immunotherapies, specifically immune checkpoint inhibitors (ICIs) PD-1/PD-L1 and CTLA-4, have become effective strategies for cancer treatment." (PMID 36426359, 2022). "Gene and protein expression analyses in lymphocytes and cancer samples after DC vaccination identified vital immunoregulatory pathways, including PD-1 and CTLA-4, which correlated with inferior clinical outcomes." (PMID 35585567, 2022). "In the clinic, anti-CTLA-4 alone or in combination with other therapeutic agents is effective in a subset of cancer patients." (PMID 35237846, 2022). "Our findings brought to light that PTX3 had a close and positive association with most ICIs (CD274, CTLA4, HAVCR2, LAG3, PDCD1, PDCD1LG2, TIGIT, and SIGLEC15) in TCGA cancers, except TGCT." (PMID 36139597, 2022). "Malignant tumors take advantage of the inhibitory programmed cell PD-1/PD-L1 or CTLA-4 pathways to evade the immune system." (PMID 36121543, 2022). "Ipilimumab is an approved anti-CTLA-4 antibody for the treatment of several cancers in combination with nivolumab (anti-PD-1 antibody)." (PMID 35813830, 2022). "Cancer immunotherapies targeting PD-1, PD-L1, and CTLA4 have achieved durable and robust responses for BC patients in clinical practice." (PMID 35401704, 2022). "Further studies are needed to study the impact of LS diet on other (non-CTLA4-based) ICI therapies on cancer immunotherapeutic efficacy and irAE incidence." (PMID 35741331, 2022). "Immune checkpoint inhibitors (i.e. ICI) represent a new Nobel-Prize worth immunotherapy with immense success in some incurable cancers, which target s inhibitory costimulatory molecules on the surface of T cells (like PD-1 or CTLA-4)." (PMID 35211124, 2022).
cancer (continued). "In cold tumors, anti-CTLA-4 treatment creates a TME that is favorable to anti-PD-1/PD-L1 antibody treatment by recruiting T cells to target cancer lesions and inducing PD-L1 expression, which provides a rationale for combination therapy." (PMID 35279217, 2022). "Immune checkpoint inhibitors that can target CTLA-4 and the programmed cell death 1 (PD-1)/programmed cell death ligand 1 (PD-L1) axis induce significantly enhanced therapeutic responses in cancer immunotherapy." (PMID 36145656, 2022). "Blocking inhibitory receptors expressed on T cells such as PD‐1 and CTLA‐4 has been a breakthrough in the treatment of cancer." (PMID 35596615, 2022). "As the main immune checkpoint inhibitors for the treatment of NSCLC, the combined treatment of PD-1/PD-L1 and CTLA-4 inhibitors has a better response and long-term cancer control, but it increases the incidence of CIP." (PMID 35464480, 2022). "Immunotherapy represented by PD-1, PD-L1 and CTLA4 has attracted great interest based on the immune regulation of cancer cells." (PMID 35155577, 2022). "Immune checkpoint inhibitors, including anti-PD-1 and anti-CTLA-4 therapies, are used to (re)activate the immune system to treat cancer." (PMID 36591246, 2022). "This work establishes an experimental foundation for potential immunotherapy treatments for cancers that include CTLA-4 and PD-1 dual inhibition." (PMID 35401745, 2022). "Accumulated evidence shows that targeting immune checkpoint regulators like PD-1/PD-L1 and CTLA-4 are significantly useful in treating cancers." (PMID 35684481, 2022). "So far, 2 important immune checkpoints with established effectiveness in cancer treatment have been investigated: the CTLA-4 pathway and the PD-1/PD-L1 pathway." (PMID 35642342, 2022). "In this review, we describe high grade DAEs to increasingly used ICB agents, which target CTLA-4 and PD-1 or its ligand, PD-L1 and enable the immune system to target cancer cells." (PMID 35770005, 2022). "Cancer immunotherapies targeting immune checkpoints, such as CTLA4 and the PD-1/PD-L1 axis, have presented substantial clinical benefits for various cancer types, such as melanoma, leukemia, and lung cancer." (PMID 36354674, 2022). "The development of immunotherapies that target T cell cosignaling is now a major focus within immunotherapy research, and the successful use of PD-1 and CTLA-4-specific monoclonal antibodies in cancer treatments has provided clear evidence of its efficacy." (PMID 35196822, 2022). "Targeting the immune checkpoints CTLA-4, PD-1, and PD-L1 help to restore the anti-cancer activity and represents the emerging trend in immunotherapeutic approaches." (PMID 35008915, 2022). "Cancer treatment with ICIs of PD-1/PD-L1 and CTLA-4 is widely used in clinical practice, but, unfortunately, it shows limited efficacy in a variety of patients due to secondary resistance or non-response." (PMID 35712510, 2022). "ICIs, especially drugs targeting PD1 and CTLA4, has become a hot spot in cancer therapy in recent years." (PMID 35387121, 2022). "Anti-tumor immune checkpoint proteins, such as PD-1/PDL1 and CTLA-4, are targets for cancer immunotherapy and have been examined in various malignant tumors." (PMID 35971106, 2022). "FDA-approved anti-CTLA-4 and anti-PD-1 antibodies for cancer treatment, which led to the belief that immunotherapy for cancer was realistic and further encouraged the development of other new ICIs." (PMID 36159861, 2022). "Yet, the clinical development of anti-CTLA4 and anti-PD-1 blocking antibodies for cancer was based on single agent treatment of highly responsive CT26 and MC38 tumors." (PMID 35937775, 2022). "In the present paper we develop a mathematical model to assess the efficacy of any combination of ADT with cancer vaccine, PD-1 inhibitor, and CTLA-4 inhibitor." (PMID 35015785, 2022). "Several clinical studies using antibodies against immune checkpoints, such as CTLA-4, PD-1, and PD-L1, had shown excellent results in numerous types of cancers." (PMID 36341387, 2022).
cancer (continued). "ICIs, such as monoclonal antibodies against PD-1, PD-L1 and CTLA-4, have greatly improved the clinical outcome of cancer patients, revolutionizing the treatment landscape for multiple tumor types." (PMID 36230887, 2022). "Immune checkpoint blockade inhibitors (CBIs) targeting cytotoxic T lymphocyte associated protein-4 (CTLA-4) and program death receptor-1 (PD-1) or its ligand-1 (PD-L1) have transformed the outlook of many patients with cancer." (PMID 35158783, 2022). "Among them, immune checkpoint inhibitors, which target PD-1, PD-L1, and CTLA-4, are increasingly used for certain cancers; however, this increased use has resulted in increased reports of immune-related adverse events (irAEs)." (PMID 36273184, 2022). "Immune checkpoints such as cytotoxic T-lymphocyte-associated protein-4 (CTLA-4), programmed cell death protein-1 (PD-1), and the associated PD-1 ligand (PD-L1) have proven effective targets in the treatment of cancer." (PMID 36077740, 2022). "ICI therapy is a promising approach to improve survival in several cancers, and some immune-checkpoint proteins, e.g., CTLA-4, PD-1, and PD-L1, are viewed as potential biomarkers of ICI response." (PMID 36010950, 2022). "Consistently, the prevalence of immune-related adverse effects is one of the major challenges in the anti-CTLA-4-based immunotherapy of cancer." (PMID 36428963, 2022). "Recently, immunotherapy, especially the inhibitor targeting immune checkpoints like CTLA-4, PD-1, or PD-L1, has achieved durable anti-tumor activity in a range of cancer types." (PMID 36276973, 2022). "Although immune checkpoint blockade (ICB) including anti-PD-1/PD-L1 and anti-CTLA4 strategies induces long-lasting responses in cancer patients, the primary and acquired resistance largely limits its clinical application." (PMID 35372044, 2022). "When an inhibitory antibody is targeted to the immune checkpoints of cytotoxic T lymphocyte-associated protein 4 (CTLA-4) and programmed death protein 1 (PD-1), it can restore immune competence in cancer patients." (PMID 35141222, 2022). "Immune checkpoint blockade such as anti-CTLA-4 and anti-PD-1/PD-L1 have been considered as promising strategies for treating various cancer types also including COAD." (PMID 35902970, 2022). "Previous studies showed that in vivo administration of CTLA4 antibodies enhanced antitumor immunity, which has promoted CTLA4 antibodies as immunotherapy for cancer." (PMID 35494032, 2022). "ICB treatments, such as targeting CTLA-4, PD-1 or PD-L1, are being clinically used for the treatment of diverse cancers." (PMID 36338702, 2022). "The nanobody binds to CTLA-4 on the surface of T cells and stimulates the immune response against cancer cells." (PMID 35933373, 2022). "As indicated, ICIs against PD-1, PD-L1, CTLA-4, and Lag3 have becoming the promising strategy for the treatments of a variety of malignancies." (PMID 36267966, 2022). "We examined the correlation between the transcriptomic expression of SPINK1 and a number of critical ICPs—PD-1, LAG-3, TIM-3, TIGIT, and CTLA-4—which are the likely signatures for the response to ICB in cancer immunotherapy." (PMID 35924241, 2022). "Other studies have reported an increased expression in CTLA-4, which was related to worse outcomes for cancer, and this is contrary to the results of this present study." (PMID 35434132, 2022). "During the last decades, therapy based on blockade of PD‐1/PD‐L1 and/or CTLA‐4 has had a remarkable impact on survival in many cancers, but the effect in hematological malignancies such as AML has been limited." (PMID 35297213, 2022). "The application of therapeutic antibodies targeting CTLA-4 such as ipilimumab became a breakthrough in cancer therapy." (PMID 35634292, 2022). "Such analyses will need to be performed in patients with other cancers and in those treated with anti-CTLA-4 checkpoint blockade." (PMID 35672305, 2022).
cancer (continued). "In anti-cancer immunotherapy, immune checkpoint blockers targeting PD-1/CTLA-4 have made a significant contribution, and these immune checkpoints are currently the most widely acknowledged biomarkers for predicting treatment response." (PMID 36092879, 2022). "This review will explore proposed mechanisms of anti-CTLA-4 involving Treg inhibition and highlights novel approaches to improve the efficacy of anti-CTLA-4 therapy while reducing its toxicity in cancer treatment." (PMID 35326731, 2022). "Immune checkpoint genes, such as CTLA-4 and PD-1, are important targets of immune checkpoint inhibitors in the treatment of various cancers." (PMID 35069733, 2022). "The associations of P4HA1 expression with LAG3, ICOS, CTLA4, CD48, TNFSF14, and CD27 expression were inconsistent among cancer types." (PMID 35812752, 2022). "Studies showing that IDO expression was also connected with resistance to anti-CTLA-4 antibodies in mice tumor models demonstrated the importance of IDO as a possible biomarker for the enrolment of cancer patients into immunotherapeutic regimens." (PMID 36016257, 2022). "Immunotherapies represented by PD-1/L1 and CTLA-4 blockades have undoubtedly emerged as a major breakthrough in cancer therapy." (PMID 36452120, 2022). "Blockade of checkpoint inhibitors, primarily CTLA-4 and PD-1/PD-1L, has in many ways revolutionized cancer therapy by unleashing effector T cell responses resulting in enhanced tumor cell killing in the local tissue environment." (PMID 36591229, 2022). "A higher ratio of cytotoxic CD8+ lymphocytes, neutrophils, T cells, and CTLA-4+ T regulatory cells was found in BALF of the cancer-affected lung compared to the healthy contralateral lung." (PMID 36552956, 2022). "Previously, several meta-analyses were focused on the CTLA-4 polymorphisms, which showed the vital role of CTLA-4 in the susceptibility to many diseases, such as cancer." (PMID 35600409, 2022). "CTLA-4 is another negative regulator expressed on T-cells, interacting with ligands on antigen-presenting cells, including cancers." (PMID 36160103, 2022). "While targeting immune suppression mechanisms in the TME has revolutionized cancer treatment, clinical trials with anti-CTLA4 or anti-PD1 only show minimal benefit in PCa patients." (PMID 36435834, 2022). "Antibodies that target PD-1/PD-L1 and CTLA4 are a well-studied and widely used method in cancer immunotherapy." (PMID 36591476, 2022). "Immunotherapy based on PD-1/PDL1 and CTLA-4 has emerged as a new pillar of cancer treatment for patients with HCC." (PMID 35627262, 2022). "Since 2011 the Food and Drugs Administration (FDA) approved an antibody against CTLA-4 (ipilimumab), two antibodies against PD-1 (pembrolizumab and nivolumab), and against PD-1 ligand 1 (atezolizumab and durvalumab) for cancer treatment." (PMID 36121543, 2022). "Antibodies that target immune checkpoints such as cytotoxic T lymphocyte antigen 4 (CTLA‐4) and the programmed cell death protein 1/ligand 1 (PD-1/PD-L1) are now a treatment option for multiple cancer types." (PMID 35634282, 2022). "Enhancers include interleukins, interferons, anti-cytotoxic T-lymphocyte-associated protein 4 (anti-CTLA4) antibodies, as well as the very currently presented genetically engineered T cells (e.g., CAR-T cells) and cancer-specific vaccines." (PMID 36171610, 2022). "Three anti-CTLA-4 antibodies have shown promising results in cancer treatment, including ipilimumab, tremelimumab, and MK1308." (PMID 35804953, 2022). "Two major ICIs, anti-programmed death protein-1 (anti-PD-1) or anti-programmed death ligand (anti-PD-L1) and anti-cytotoxic T-lymphocyte-associated protein 4 (anti-CTLA-4), are currently approved to treat many cancer types, including solid tumors." (PMID 35265206, 2022). "MOA of the immunotherapeutic drugs, also called checkpoint inhibitors, is to block PD-1, PD-L1, or CTLA-4 proteins on the immune cells and increase cytotoxic T-cell activity against cancer cells." (PMID 35842448, 2022).
cancer (continued). "The two most clinically relevant checkpoints, CTLA4 and PD-1, act as brakes on the anti-cancer immune response." (PMID 35911673, 2022). "Chronic and prolonged exposure to antigens in cancer leads to increased expression of CTLA-4 and PD-1 resulting in acquired tolerance of antigens, thus nullifying effector functions such as cytokine production, cytotoxicity, and T cell proliferation." (PMID 36164594, 2022). "The IPS values (ips_ctla4_neg_pd1_pos, ips_ctla4_pos_pd1_neg, ips_ctla4_pos_pd1_neg, and ips_ctla4_pos_pd1_pos) have been reported in predicting cancer patients’ responses to anti-CTLA-4 treatment." (PMID 36686785, 2022). "Immune checkpoint blockades, such as sole and dual CTLA-4 and PD-1/PD-L1 blockades, have already represented a clinical benefit for several cancers including LUAD." (PMID 35620481, 2022). "Studies have shown that PD1 and CTLA4 inhibitors have therapeutic potential in a variety of cancers, some of which have been approved for cancer treatments." (PMID 35444953, 2022). "On the other hand, blocking the CTLA-4 by Anti-CTLA-4 antibodies was shown to remove the immune barrier to cancer and demonstrated as promising cancer therapy." (PMID 36482486, 2022). "Immune checkpoint inhibitors, including those targeting PD-1, PD-L1, PD-L2, and CTLA4, are considered the primary therapy for many malignant tumors." (PMID 36110218, 2022). "It is an uncommon adverse event, estimated below 3% in patients receiving ICI treatments for cancer, and is more frequent with anti-PD-1 than with anti-CTLA-4 antibodies." (PMID 36140517, 2022). "As such, these pre-clinical investigations define a clear pathway for employing hydrogel-encapsulated anti-CTLA-4 as a strategy for improving the tolerability and potency of cancer immunotherapy." (PMID 35621582, 2022). "This would be an area of future direction using a larger cohort with a broader cancer therapeutic regimen including more anti-CTLA-4 and/or concurrent chemotherapy." (PMID 36345032, 2022). "CTLA-4 expressed on Treg cells can induce cancer regulatory effects via interaction with forkhead box P3 (FOXP3)." (PMID 36423060, 2022). "For instance, cancer cells can use immune checkpoint genes such as PD-1 and CTLA-4 to evade immune surveillance." (PMID 36081989, 2022). "Antibodies targeting CTLA-4 are approved in multiple cancers including; metastatic melanoma, hepatocellular, renal carcinoma, mesothelioma, colon cancer, and non-small cell lung cancer, and more will be included in the near future." (PMID 35784333, 2022). "Immune checkpoint inhibitors such as PD-L1, PD-1 and CTLA-4 antibodies all assist the body’s own immune cells to exert cytotoxic effects to kill cancer cells." (PMID 36540802, 2022). "Immune checkpoint blockade (ICB) therapies targeting programmed cell death 1 (PD‐1) or ligand 1 (PD‐L1) and cytotoxic T‐lymphocyte antigen‐4 (CTLA‐4) have demonstrated higher efficacy than standard therapies in several cancers." (PMID 35229456, 2022). "Immune checkpoint inhibition is a mechanism that inhibits the expression of immune checkpoint proteins, such as PD-1/PD-L1 and cytotoxic T-lymphocyte antigen (CTLA)-4/B7-1/B7-2, expressed on T cells or cancer cells." (PMID 36555393, 2022). "The TIMER2 database is used to compare the expression levels of PD-1/PD-L1/CTLA-4 in pan-cancer and corresponding adjacent tissues." (PMID 36147250, 2022). "LAG-3 inhibitors, together with CTLA-4 or PD-1/PD-L1 inhibitors, have been extensively explored in the different clinical trials for cancer therapy, which can not only avoid drug tolerance but also improve the clinical efficacy of LAG-3 inhibitors." (PMID 35958563, 2022). "PD1/PD-L1 and CTLA-4 are well-known immune checkpoints that play instrumental roles in cancer treatment modalities due to immune surveillance and escape." (PMID 36686785, 2022). "Immunotherapy using anti-PD-1/CTLA-4 drugs has achieved encouraging success in clinical anti-cancer treatment regimens.." (PMID 35606813, 2022).